KAT8 (lysine acetyltransferase 8)
Diseases named in the same sentence as KAT8 in open-access papers (continued):
Sharing a sentence is not in itself a finding about the gene and the disease.
glioma (4 papers, 2019 to 2025). A benign or malignant brain and spinal cord tumor that arises from glial cells (astrocytes, oligodendrocytes, ependymal cells). "KAT8 expression was significantly higher in glioma patients with IDH mutations compared to those with wild‐type IDH (WT)." (PMID 40259204, 2025). "The association between KAT8 expression and various clinicopathological features provides insights into its biological significance in gliomas." (PMID 40259204, 2025). "The findings reveal that KAT8 expression is intricately linked to a diverse array of central nervous system tumours." (PMID 40259204, 2025). "However, high KAT8 expression is associated with a significantly higher survival rate in grade IV gliomas." (PMID 40259204, 2025). "The differential expression profile was characterised by a number of up‐regulated and down‐regulated genes, which may offer insights into the molecular mechanisms underlying KAT8's role in gliomas." (PMID 40259204, 2025). "Additionally, we conducted function analyses to elucidate the potential molecular mechanisms underlying KAT8's role in glioma progression." (PMID 40259204, 2025). "Furthermore, across all glioma subtypes, KAT8 is positively linked to stemness attributes." (PMID 40259204, 2025). "The differential expression and prognostic significance of KAT8 across glioma grades suggest that targeting KAT8 or its associated pathways could offer new avenues for glioma treatment, particularly in high‐grade tumours where its expression correlates with improved survival." (PMID 40259204, 2025). "Our study offers important insights into the role of KAT8 in glioma cell apoptosis and EV‐A71 infection." (PMID 40259204, 2025). "Analysis of the Receiver Operating Characteristic (ROC) curve indicates that the expression of the KAT8 gene demonstrates a commendable degree of accuracy in predicting the presence of disease among glioma patients, encompassing both GBM and LGG cases." (PMID 40259204, 2025). "We found that the expression of KAT8 was significantly higher in glioma patients with 1p19q co‐deletion (Codel group) than in those without 1p19q co‐deletion (Non‐Codel group)." (PMID 40259204, 2025). "This study aimed to investigate the expression patterns of KAT8 under OV infection and in glioma tissues and also to evaluate its potential as a prognostic biomarker." (PMID 40259204, 2025). "This study focused on KAT8, a key lactylation enzyme, and its potential role in glioma progression and prognosis." (PMID 40259204, 2025). "To verify the function of KAT8 mediated by EV‐A71 infection in glioma cells, we infected U87 and A172 cells with EV‐A71." (PMID 40259204, 2025). "KAT8 was significantly overexpressed in glioma tissues compared to normal brain tissues, with higher expression in lower‐grade gliomas." (PMID 40259204, 2025). "The single‐cell sequencing results in the previous section suggested that KAT8 functions most closely with apoptosis in gliomas." (PMID 40259204, 2025). "The RNA‐seq data after oncolytic virus EV‐A71 infection on glioma cells was analysed to screen and lysine acetyltransferase 8 (KAT8) was selected." (PMID 40259204, 2025). "Based on the close relationship between KAT8 expression and glioma function, we next examined the expression of KAT8 in glioma cell lines." (PMID 40259204, 2025). "This contradicts its association with better prognosis and highlights the complex nature of KAT8's role in glioma biology." (PMID 40259204, 2025). "The functional annotations and single‐cell sequencing analyses provide insights into the potential mechanisms of KAT8 action in gliomas." (PMID 40259204, 2025). "This value reflects the discriminative power of KAT8 expression in distinguishing glioma patients from healthy individuals." (PMID 40259204, 2025). "We analysed KAT8 expression in glioma tissues using data from The Cancer Genome Atlas (TCGA) and Genotype‐Tissue Expression (GTEx) databases." (PMID 40259204, 2025).
glioma (continued). "In vitro experiments confirmed the increased apoptosis in glioma cell lines following KAT8 knockdown." (PMID 40259204, 2025). "The dual functionality of KAT8 in both acetylation and lactylation processes suggests a complex interplay between these post‐translational modifications in the context of glioma development and progression." (PMID 40259204, 2025). "In vitro experiments were conducted to validate the effects of KAT8 knockdown on apoptosis in glioma cells." (PMID 40259204, 2025). "KAT8 was among the top 5 down‐regulated genes in glioma cells after oncolytic viruses EV‐A71 infection." (PMID 40259204, 2025). "To further elucidate the expression and significance of KAT8 in glioma tissues, we randomly selected 5 clinical tissue specimens of varying WHO grades (1 WHO grade I sample, 2 WHO grade III samples and 2 WHO grade IV samples), as well as 5 normal brain tissue samples obtained from epilepsy surgery." (PMID 40259204, 2025). "Notably, our results revealed that KAT8 was significantly up‐regulated in glioma tissues across all WHO grades, at both the mRNA and protein levels." (PMID 40259204, 2025). "The higher KAT8 expression in the Codel group could reflect a metabolic shift or altered cellular behaviour in glioma, which may contribute to their distinct clinical outcomes." (PMID 40259204, 2025). "Understanding these molecular mechanisms may provide new insights into glioma biology and potentially lead to novel therapeutic strategies targeting KAT8‐mediated pathways in glioma treatment." (PMID 40259204, 2025). "Notably, KAT8 was among the top five down‐regulated genes in glioma cells following EV‐A71 infection." (PMID 40259204, 2025). "Through comprehensive bioinformatics analyses of publicly available datasets, we examined KAT8 expression levels across different glioma grades and subtypes, assessed its correlation with patient survival, and explored its association with various clinicopathological features." (PMID 40259204, 2025). "This protective effect, confirmed by multivariate Cox analysis, suggests that KAT8 might play a complex, context‐dependent role in glioma biology." (PMID 40259204, 2025). "However, recent research has identified KAT8 as a potential lactylation regulator, warranting further exploration of its role in glioma biology." (PMID 40259204, 2025). "Our present study revealed that EV‐A71 infection could be a powerful enhancer of cell apoptosis by increasing KAT8 expression levels in glioma." (PMID 40259204, 2025). "We next investigated the relationship between KAT8 expression and prognosis in glioma patients." (PMID 40259204, 2025). "Notably, high KAT8 expression correlated with better overall survival in grade IV gliomas." (PMID 40259204, 2025). "Therefore, high KAT8 expression in grade IV gliomas may provide valuable prognostic information and guide the development of therapeutic strategies." (PMID 40259204, 2025). "The results showed that the expression level of KAT8 was significantly higher in some tumour tissues than in normal tissues, such as in glioma (including GBM and LGG), CHOL, PAAD, and THYM." (PMID 40259204, 2025). "The expression of KAT8 is significantly higher in glioma patients with 1p19q co‐deletion compared to those without 1p19q co‐deletion." (PMID 40259204, 2025). "However, the expression and role of lactylation enzyme KAT8 in glioma have not been previously reported." (PMID 40259204, 2025). "Patients with high or low KAT8 expression exhibited similar survival outcomes, suggesting that KAT8 expression may not have a direct impact on prognosis in lower‐grade gliomas." (PMID 40259204, 2025). "However, the absence of a significant difference between grades I–III could indicate that KAT8 expression is not a reliable discriminator for tumour grade in lower‐grade gliomas, pointing to the need for further investigation into its specific role in glioma progression." (PMID 40259204, 2025).
epilepsy (3 papers, 2020 to 2025). A brain disorder characterized by episodes of abnormally increased neuronal discharge resulting in transient episodes of sensory or motor neurological dysfunction, or psychic dysfunction. "Similarly, patients with KAT8 mutations presented with variable brain MRI abnormalities, epilepsy, global developmental delay, ID, facial dysmorphisms, variable language delay, and other developmental anomalies." (PMID 33263776, 2021). "Interestingly, patients with epilepsy responded well to the histone deacetylase inhibitor Valproate, stressing the importance of KAT8 and other lysine acetyltransferases function in brain development." (PMID 33263776, 2021).
Intellectual disability (3 papers, 2022 to 2025). "The study also reported that KAT8 variants in patients are associated with intellectual disability, seizures, autism, dysmorphisms, and other anomalies, suggesting a link between deficient H4K16 acetylation and intellectual disability." (PMID 35794091, 2022).
Parkinson disease (3 papers, 2022 to 2024). A progressive degenerative disorder of the central nervous system characterized by loss of dopamine producing neurons in the substantia nigra and the presence of Lewy bodies in the substantia nigra and locus coeruleus. "It has recently been shown that KAT8, a genome-wide association study candidate risk gene for Parkinson’s Disease, is involved in PINK1/Parkin-dependant mitophagy." (PMID 38777823, 2024). "A study on Parkinson’s disease reported that KAT8 is a potentially causal gene based on GWAS and differential gene expression, implying that KAT8 may have a common role in the neurodegeneration of AD and Parkinson’s disease." (PMID 35656316, 2022). "To gain further insight into a possible role for KAT8 in the aetiology of Parkinson’s disease, we explored the known functional interactions of this protein." (PMID 36074904, 2022).
Virus Infection (3 papers, 2024 to 2025). "In summary, our findings highlight KAT8 as a significantly down‐regulated gene during oncolytic virus infection." (PMID 40259204, 2025). "Through histone acetylation, KAT8 works as a critical regulator of immune cell behavior under stress conditions, such as viral infections." (PMID 38790268, 2024). "Virus infection increased HDAC3 expression in PK-15 cells, which inversely correlated with KAT8 and mediated PHGDH deacetylation." (PMID 39207107, 2024). "However, KAT8 can also influence macrophage function in response to viral infections by directly acetylating a non-histone protein, interferon regulatory factor 3 (IRF3)." (PMID 38790268, 2024). "The negative correlation between KAT8 expression and apoptosis in GBM cells, coupled with the increased apoptosis observed in oncolytic virus infection, indicates a potential anti‐apoptotic function." (PMID 40259204, 2025).
acute myeloid leukemia (2 papers, 2023 to 2024). Acute myeloid leukemia (AML) is a group of neoplasms arising from precursor cells committed to the myeloid cell-line differentiation. "KAT8 dysregulation is linked to thedevelopment and metastatization of many cancer types, including non-smallcell lung cancer (NSCLC) and acute myeloid leukemia (AML)." (PMID 37155735, 2023). "Furthermore, studies show that KAT8 influences acute myeloid leukemia (AML) differentiation by suppressing MN1 (meningioma 1) expression, a gene associated with rapid leukemia onset when overexpressed." (PMID 38790268, 2024).
Bladder Cancer (2 papers, 2024 to 2025). "It downregulated KAT8 and H4K16ac levels in T24 bladder cancer cells, upregulated cleaved poly(ADP-ribose) polymerase 1 (PARP1), downregulated BCL2, and promoted apoptosis." (PMID 40508066, 2025).
cervical carcinoma (2 papers, 2015 to 2025). A carcinoma arising from either the exocervical squamous epithelium or the endocervical glandular epithelium. "For example, KAT8 increased H4K16ac levels in the promoter region of the human papillomavirus oncoprotein E7 in cervical cancer cells, enhancing transcriptional activity and accelerating proliferation." (PMID 40508066, 2025). "Rapamycin suppressed KAT8 levels and H4K16ac levels, promoting the conversion from LC3-I to LC3-II and activating autophagy in HeLa cervical cancer and U1810 NSCLC cells." (PMID 40508066, 2025).
Hypertension (2 papers, 2019 to 2024). The presence of chronic increased pressure in the systemic arterial system. "In summary, in the absence of caffeine, TERF2IP binds preferentially to the reference allele at rs4527034, which results in lower expression of KAT8 and reduced risk for hypertension." (PMID 38334359, 2024). "INTACT associated high expression of KAT8 with increased risk of hypertension." (PMID 38334359, 2024). "In the presence of caffeine, TERF2IP is upregulated, resulting in increased binding and lower expression of KAT8, independently of the genotype, with an expected overall protective effect on hypertension." (PMID 38334359, 2024).
leukemia (2 papers, 2022 to 2025). A malignant (clonal) hematologic disorder, involving hematopoietic stem cells and characterized by the presence of primitive or atypical myeloid or lymphoid cells in the bone marrow and the blood. "Knockout/overexpression of KAT8 correlated positively with phosphorylation of serine 139 in H2A.X variant histone (H2AX), a DNA damage marker (γH2AX), in MLL-AF9 leukemia cells, indicating that KAT8 promotes DNA damage repair and inhibits apoptosis in AF9 cells." (PMID 40508066, 2025).
neuroblastoma (2 papers, 2016 to 2025). Neuroblastoma (NB) is the most common solid, extracranial childhood tumor. "Additionally, treating neuroblastoma cells with MG149, a KAT8 inhibitor, impairs global H4K16 acetylation and autophagy regulator PTEN-Induced Kinase 1 (PINK1) expression of neuroblastoma cells further inhibiting autophagy receptor p62 recruitment, resulting in autophagy." (PMID 40508066, 2025).
22q11.2 deletion syndrome (1 paper, 2025). 22q11.2 deletion syndrome (DS) is a chromosomal anomaly which causes a congenital malformation disorder whose common features include cardiac defects, palatal anomalies, facial dysmorphism, developmental delay and immune deficiency. "Differential diagnosis encompasses other chromosomal deletions such as 22q11.2 deletion syndrome and other pathogenic variants such as lysine acetyltransferase 6B (KAT6B) and lysine acetyltransferase 8 (KAT8)." (PMID 40115715, 2025).
asthma (1 paper, 2026). "Here, we demonstrate that histone acetyltransferase KAT8 exacerbates allergic airway inflammation by promoting M2 macrophage polarization in asthma." (PMID 41952982, 2026).
astrocytoma (1 paper, 2025). "In astrocytoma (AST), KAT8 levels demonstrate a positive correlation with invasion characteristics." (PMID 40259204, 2025).
astroglioma (1 paper, 2022). "The effect of the KAT8 and KANSL1 KD on pUb(Ser65) was confirmed in WT SHSY5Y cells and the astroglioma H4 cell line, both of which are expressing endogenous levels of Parkin." (PMID 36074904, 2022).
developmental delay (1 paper, 2025). "Pathogenic variants in KAT8, encoding lysine acetyltransferase‐8, lead to Li–Ghorgani–Weisz–Hubshman syndrome (MIM 618974), characterized by global developmental delay, seizures, dysmorphic features, and behavioral issues, with variable brain abnormalities." (PMID 41438488, 2025).
endometrial cancer (1 paper, 2025). Primary or metastatic malignant neoplasm involving the endometrium (mucous membrane that lines the endometrial cavity). "Similarly, upregulating KAT8 promoted the proliferation, migration, and invasion of endometrial cancer Ishikawa cells." (PMID 40508066, 2025).
esophageal squamous cell carcinoma (1 paper, 2025). Esophageal squamous cell carcinoma (ESCC) is a type of esophageal carcinoma (EC) that can affect any part of the esophagus, but is usually located in the upper or middle third. "In oesophageal squamous cell carcinoma (ESCC) cells, KAT8 catalyzed the acetylation of fascin actin-bundling protein 1 (FSCN1) at lysine 41, enhancing its F-actin-bundling activity and promoting filopodia/invadopodia formation to drive ESCC cell invasion." (PMID 40508066, 2025).
gastric tumor (1 paper, 2023). "Finally, we determined the levels of K235 acetylation and ALKBH5, KAT8, and HDAC7 in ten pairs of matched fresh primary liver and gastric tumor samples and adjacent nontumor liver and gastric tissues." (PMID 37369679, 2023).
heart failure (1 paper, 2024). Inability of the heart to pump blood at an adequate rate to meet tissue metabolic requirements. "AAV9-mediated upregulation ofmitochondrial KAT8 in cardiomyocytes under the control of the cardiac troponin Tpromoter was sufficient to induce heart failure in mice." (PMID 39958699, 2024).
insomnia (1 paper, 2022). A sleep disorder characterized by difficulty in falling asleep and/or remaining asleep. "Consequently, we highlighted the potentially interesting functions of the novel associations for PRL (6p22.3) between AD and snoring, as well as the focused PTPMT1(11p11.2) and KAT8(16p11.2) regions shared between AD and insomnia or sleep duration." (PMID 35656316, 2022).
Lewis lung carcinoma (1 paper, 2023). "In vivo, KAT8 depletion in the Lewis lung carcinoma cell line LLC1 inhibited tumor growth and reduced tumor weight while increasing the tumor infiltration of CD3+CD8+ T cells in mice." (PMID 36894639, 2023).
Li-Ghorbani-Weisz-Hubshman syndrome (1 paper, 2024). "KAT8 variants are linkedto Li- Ghorbani-Weisz-Hubshman syndrome (LIGOWS), which presents heart anomalies inapproximately half of the patients." (PMID 39958699, 2024).
lysosomal disorder (1 paper, 2023). "KAT8 is a key regulator of autophagy, and the presence of a GWAS hit near KAT8 has been cited as evidence in support of PD being a “lysosomal disorder”." (PMID 37328865, 2023).
malignant glioma (1 paper, 2025). A grade III or grade IV glioma arising from the central nervous system. "Conversely, silencing KAT8 in malignant glioma cells downregulated cyclin-dependent kinase 1 (CDK1), cyclin A, and cyclin B expression and upregulated p21 expression, leading to G2/M-phase arrest." (PMID 40508066, 2025).
prostate tumor (1 paper, 2017). "MYST1/KAT8 also controls the activity of androgen target genes and its knockdown reduces prostate tumor cell proliferation." (PMID 28486411, 2017).
thyroid cancer (1 paper, 2025). "Consistent with this, KAT8 deficiency promoted apoptosis in BHP-10-3 and TT2609 thyroid cancer cells." (PMID 40508066, 2025). "In thyroid cancer tissues with high KAT8 expression, KAT8 knockdown decreased the levels of cyclin D1 (CCND1) and D3 (CCND3), critical regulators of the G1/S transition, resulting in G1-phase cell cycle arrest and suppressed thyroid cancer cell proliferation." (PMID 40508066, 2025).